SF3B5 (splicing factor 3b subunit 5)
Description:
Component of the 17S U2 SnRNP complex of the spliceosome, a large ribonucleoprotein complex that removes introns from transcribed pre-mRNAs. The 17S U2 SnRNP complex (1) directly participates in early spliceosome assembly and (2) mediates recognition of the intron branch site during pre-mRNA splicing by promoting the selection of the pre-mRNA branch-site adenosine, the nucleophile for the first step of splicing. Within the 17S U2 SnRNP complex, SF3B4 is part of the SF3B subcomplex, which is required for 'A' complex assembly formed by the stable binding of U2 snRNP to the branchpoint sequence in pre-mRNA. Sequence independent binding of SF3A and SF3B subcomplexes upstream of the branch site is essential, it may anchor U2 snRNP to the pre-mRNA. Also acts as a component of the minor spliceosome, which is involved in the splicing of U12-type introns in pre-mRNAs.
Synonyms: SF3B10; MGC3133; Ysf3
Tractability: Small molecule: a structure with a bound ligand is known. PROTAC: ubiquitination databases record sites on it; its protein half-life has been measured.
Target class: Other nuclear protein
Gene: Protein-coding gene on chromosome 6 (144,094,884 to 144,095,573, reverse strand). Ensembl gene ENSG00000169976.
Subcellular location: Nucleus
Subcellular location (Human Protein Atlas): Nucleoplasm
Pathways (Reactome):
Metabolism of RNA: mRNA Polyadenylation; mRNA Splicing - Major Pathway; mRNA Splicing - Minor Pathway
Chromatin organization: CHD1 and CHD2 subfamily
Disease: Dengue Virus-Host Interactions
Gene Ontology:
Molecular function: protein binding; RNA binding; splicing factor binding
Biological process: mRNA splicing, via spliceosome; positive regulation of DNA-templated transcription; regulation of DNA repair; regulation of RNA splicing; spliceosomal snRNP assembly; spliceosome conformational change to release U4 (or U4atac) and U1 (or U11); U2-type prespliceosome assembly
Cellular component: nucleoplasm; nucleus; precatalytic spliceosome; spliceosomal complex; U11/U12 snRNP; U12-type catalytic step 2 spliceosome; U12-type precatalytic spliceosome; U12-type spliceosomal complex; U2-type catalytic step 1 spliceosome; U2-type precatalytic spliceosome; U2-type spliceosomal complex; SAGA complex; U2 snRNP
Genetic constraint (gnomAD): Loss-of-function variants: 3 observed, 7.61 expected, observed/expected ratio (o/e) 0.39, 90% interval 0.18 to 1.02. That is too few expected variants to judge how well the gene tolerates losing a copy. Missense variants: 73 observed, 122.37 expected, observed/expected ratio (o/e) 0.6, 90% interval 0.49 to 0.73. Synonymous variants: 51 observed, 49.2 expected, observed/expected ratio (o/e) 1.04, 90% interval 0.83 to 1.31.
Homologues: Orthologues: chimpanzee SF3B5 (100% identical), dog SF3B5 (100% identical), guinea pig SF3B5 (100% identical), pig SF3B5 (100% identical), rabbit SF3B5 (100% identical), mouse Sf3b5 (99% identical), rat Sf3b5 (99% identical), tropical clawed frog sf3b5 (95% identical), zebrafish sf3b5 (94% identical), Drosophila melanogaster Sf3b5 (83% identical).
Diseases named in the same sentence as SF3B5 in open-access papers:
SF3B5 is named in the same sentence as 7 diseases in open-access papers, as found by Europe PMC text mining. Sharing a sentence is not in itself a finding about the gene and the disease. The quoted sentences say what the papers report.
ovarian carcinoma (2 papers, 2021). A malignant neoplasm originating from the surface ovarian epithelium. "It has been suggested that SF3B5 is a key prognostic factor in ovarian cancer." (PMID 35126467, 2021). "Our splicing regulation network analysis showed some splicing factors might be correlated with prognosis-related AS events, including SPEN, SF3B5, RNPC3, LUC7L3, SRSF11 and PRPF38B, suggesting that these splicing factors could play crucial roles in ovarian cancer development." (PMID 34001978, 2021).
tumor (3 papers, 2021 to 2025). "Our results demonstrate that SF3B5 is monoallelically expressed in many tumor cell lines, suggesting that it may be imprinted or monoallelically expressed due to other mechanisms in these cell lines." (PMID 40414875, 2025). "In addition, survival-related AS events might be involved in tumor-related pathways including base excision repair and pyrimidine metabolism pathways, and some splicing factors might be correlated with prognosis-related AS events, including SPEN, SF3B5, RNPC3, LUC7L3, SRSF11 and PRPF38B." (PMID 34001978, 2021).
SF3B5 also shares sentences with these, for which no sentence is quoted: acute myeloid leukemia (1 paper); breast carcinoma (1); cancer (1); endothelial dysfunction (1); muscular dystrophy (1).